SKP2 (S-phase kinase associated protein 2)
Diseases named in the same sentence as SKP2 in open-access papers (continued):
Sharing a sentence is not in itself a finding about the gene and the disease.
cancer (continued). "Pursuant to our previous finding that upregulation of β-transducin repeat-containing protein (β-TrCP) expression represents a cellular response in cancer cells to ERMAs, including CG-12 and 2-deoxyglucose, we demonstrated that this β-TrCP accumulation resulted from decreased Skp2 expression." (PMID 23071779, 2012). "Together, these findings indicate an intricate relationship between Skp2 and β-TrCP in energy-restricted cancer cells in which downregulated Skp2 expression is involved in the glycolysis inhibitor-induced accumulation of β-TrCP, which in turn contributes to the reduced expression of Skp2." (PMID 23071779, 2012). "In addition, the prognostic significance and overexpression of SKP2 in a variety of human cancers, combined with observations that SKP2 knockout mice are both viable and fertile, further strengthens its appeal." (PMID 23226679, 2012). "Skp2, as an oncogenic protein, plays a pivotal role in various types of cancers." (PMID 23300741, 2012). "This feedback loop represents a novel crosstalk mechanism between these two important F-box proteins in cancer cells with aberrant Skp2 expression under energy restriction, which provides a proof-of-concept that the oncogenic Csn5/Skp2 signaling axis represents a “druggable” target." (PMID 23071779, 2012). "Although this crosstalk mechanism occurs in a cellular context different from that of cell cycle regulation, it provides a molecular basis to account for the antitumor effects of ERMAs by upregulating β-TrCP-mediated apoptosis signaling in cancer cells with aberrant Skp2 expression." (PMID 23071779, 2012). "SKP2 overexpression could protect cancer cells from anoikis, which was mediated in part by the phosphoinositidyl 3-kinase-Akt pathway." (PMID 22920630, 2012). "Furthermore, high SKP2 expression was observed to correlate with low p27KIP1 expression levels, consistent with studies in other cancer types." (PMID 23226679, 2012). "In conclusion, Skp2 plays an oncogenic role in the development and progression of human cancers through degradation of its downstream target proteins that control a variety of cellular processes such as cell proliferation, apoptosis, migration, invasion and metastasis." (PMID 23230084, 2012). "Skp2 has oncogenic potential and is overexpressed in human cancers." (PMID 21386910, 2011). "The notion is supported by various genetic mouse models that demonstrate an oncogenic activity of Skp2 and its requirement in cancer progression, suggesting that Skp2 may be a novel and attractive therapeutic target for cancers." (PMID 20526532, 2010). "Now cancer therapeutic strategies targeting Skp-2 are becoming a hot topic." (PMID 21182801, 2010). "Skp2 over-expression has been observed in many human cancers." (PMID 19549334, 2009). "As a result, Skp2 degradation is protected in cancer cells with elevated Akt activity." (PMID 19549334, 2009). "Furthermore, since elevated Akt also inactivates the Bad, Caspase-9 and FOXO proteins to allow tumor cells to evade the apoptosis pathway, cancer cells with cytoplasmic Skp2 localization tend to be more advanced." (PMID 19549334, 2009). "At first glance, this offers a molecular mechanism for the frequently observed Skp2 overexpression in many human cancers and links this phenomenon to the abnormal activation of the PI 3-K and Akt pathway, which is well-documented as being aberrantly activated in the majority of human cancers." (PMID 19549334, 2009). "In contrast to the frequency of Skp2 overexpression, loss of Cdh1 is not a frequent event in human cancer." (PMID 19549334, 2009). "The role of Skp2 as the main rate-limiting regulator p27Kip1 degradation has been clearly demonstrated in both intact cells and in cell-free systems, as well as in many human cancers." (PMID 18644126, 2008). "Elevated levels of skp2 correlate with cancer where cells proliferate inappropriately." (PMID 18081928, 2007).
cancer (continued). "SKP2 inhibitors may be useful to treat RB-deficient cancers for which CDK4 inhibitors are ineffective and also show efficacy in resensitizing drug-resistant cancers and synergistic effects with other drugs." (PMID 40002221, 2025). "In addition, YAP/TAZ participates in cell mitosis and DNA replication, promotes cell cycle and maintains the expression of oncogene transcription factors, such as activator protein 1 (AP-1) and Skp2, through direct transcription and induction of cancer cell lines." (PMID 38553612, 2024). "mTOR inhibitor treatment in non-cancer cell lines increases polyomavirus LT-antigen expression and directly activates polyomavirus replication by inhibiting S-phase kinase-associated protein 2 (Skp2) E3 ligase at non-cytotoxic concentrations." (PMID 38940554, 2024). "Targeting SKP2 or its downstream signaling pathways may represent a potential approach to mitigate immune evasion and enhance the immune system’s ability to recognize and eliminate cancer cells." (PMID 38559562, 2024). "However, the molecular mechanisms and the cause of p27 gene loss and elevated levels of Skp2 gene expression are not wholly investigated in all cancer types." (PMID 38559562, 2024). "Interestingly, our study identified Skp2 expression to be altered in a cancer-specific manner." (PMID 38559562, 2024). "In addition, overexpression of Skp2 is observed in numerous human cancers." (PMID 37089937, 2023). "MUC1 has been associated with the progression of GBC, and Skp2 may be an independent prognostic factor for GBC; these studies suggested the potential roles of these factors in the occurrence and development of cancer." (PMID 36624399, 2023). "These evidences suggest that Moesin might function as an upstream regulator to stabilize these oncoproteins (including SKP2), aggravate cancer progression and correlate with poor patient prognosis, and therefore could serve as a potential target for cancer therapy." (PMID 37736741, 2023). "Moreover, YAP increases nucleic accumulation of P27, a cell cycle suppressor by acetylating and nucleic-exporting S-phase kinase associated protein 2 (SKP2) via Akt activation to sustain cytoplasm retention of SKP2 and to inhibit mitosis of cancer cells, which causes polyploidy formation." (PMID 36906534, 2023). "However, whether SKP2 affects the process of cancer through an olfactory transmission mechanism requires further experimental verification." (PMID 37308972, 2023). "Skp2 is elevated in human cancer and may be crucial for the progression of cancer." (PMID 37964867, 2023). "However, besides cancers, Skp2 was also reported to associate with other non-cancer diseases, such as chronic kidney disease, pulmonary Fibrosis, systemic dysregulation of COVID-19 patients, and asthma as well." (PMID 37089937, 2023). "Thus, AKT-Moesin-SKP2 axis may be explored for the development of therapeutics for cancer treatment." (PMID 37736741, 2023). "It is noteworthy that, based on the GSEA focusing on a common potential molecular mechanism in different neoplasms, the olfactory transduction pathway may also be essential for SKP2 to affect cancer progression, as the pathway was observed in up to 11 neoplasms." (PMID 37308972, 2023). "In addition to being involved in Akt-mediated cancer development, Skp2 is also required for tumorigenesis upon pRb or p19Arf inactivation, suggesting that Skp2 may serve as a common downstream effector for tumorigenesis driven by various oncogenic signals." (PMID 36180910, 2022). "Therefore, CDK2 is a critical molecule that modulates the SKP2/P27 axis in human cancers." (PMID 35313079, 2022).
cancer (continued). "Moreover, SKP2 has established proteolytic targets such as P27 and Cyclin E1, which are oncogenes frequently amplified at the level of the genome in many cancers, including ~20% and ~23% of CRC cases, respectively." (PMID 36496990, 2022). "Thus, the results of these previous studies and those of the current study are consistent with SKP2 expression and function being tightly regulated to ensure accurate cell cycle progression, maintain genome stability, and prevent cancer development (i.e., tumor suppressor-like activity)." (PMID 36496990, 2022). "When Skp2 (S-phase kinase associated protein 2) is overexpressed, cancer growth could not be suppressed effectively." (PMID 34836055, 2021). "Thus, the Skp2-p27 pathway is a critical target for cancer therapy." (PMID 34572430, 2021). "Therefore, Skp2 may be a crucial target for various cancers in which Skp2 is abnormally activated or overexpressed." (PMID 34943817, 2021). "Similarly, amplification and overexpression of SKP2 promotes the increased degradation of P27 and disease progression and is associated with worse survival outcomes and poor response to therapy in numerous cancer types, contributing to SKP2 being traditionally classified as an oncogene." (PMID 35008511, 2021). "In addition, it was proven by RNA seq that the key to 4F2hc’s impact on cancer is SKP2." (PMID 34075107, 2021). "Therefore, 20(S)-Rh2E2 is a potent anti-cancer agent by suppressing Skp2." (PMID 32796841, 2020). "In addition, it can be assumed that in the described relationship between CsA therapy and an increased risk of cancer, the SKP2 and PRKR2B genes are not involved or their role is marginal." (PMID 32774143, 2020). "Thus, MLN4924 is a promising approach to exploit the SKP2-dependency of RB1 null cancers." (PMID 32123578, 2020). "Moreover, high expression of Skp2 is correlated with poor survival in human cancer patients." (PMID 32626765, 2020). "Furthermore, SKP2 plays important roles in cancer metastasis via decreasing the expression of p27." (PMID 30999935, 2019). "Additionally, Skp2 has been found to attenuate p57 function in human cancers." (PMID 30847385, 2019). "The present study demonstrated that sja-miR-7-5p is present in infected hepatocytes, selectively affects the growth and migration of human and mouse tumor cells by targeting the SKP2 gene, implying that sja-miR-7-5p might strengthen resistance of host to cancer during schistosome infection." (PMID 30967999, 2019). "S-phase kinase-associated protein 2 (Skp2) regulates phosphorylated cell cycle regulator proteins and their ubiquitination as a cell cycle regulator and oncogene, c-Myc also works as an oncogene and cell cycle regulator, while PI3K and AKT are considered typical survival proteins in several cancers." (PMID 31426282, 2019). "Thus, the pharmacological suppression of SKP2 may prove to be a potent chemotherapeutic strategy to overcome drug resistance due to EMT reversal in various human cancers." (PMID 30999935, 2019). "Therefore, the inhibition of SKP2 could be a novel strategy for the treatment of some human cancers." (PMID 29594129, 2018). "Importantly, 83 out of 169 cancer tissues examined contained high expression of p-mTOR, whereas 68 out of the 88 tissues containing active Skp2, supporting the conclusion that activation of mTOR signaling is involved in the overproduction of Skp2." (PMID 28446188, 2017). "However, the role of cytoplasmic expression of Skp2 in cancers remains undefined." (PMID 23300741, 2012).
cancer (continued). "In light of the therapeutic potential of targeting Csn5/Skp2 in cancer treatment, the ability of CG-12 to downregulate the expression of Csn5 and Skp2 through Sirt1 induction provides a proof-of-concept that the Csn5/Skp2 signaling axis represents a “druggable” target for this novel ERMA." (PMID 23071779, 2012). "Therefore, p27 depletion can be reversed by small molecules in cancer cells overexpressing SKP2." (PMID 21182779, 2010). "Therefore, Skp2 upregulation in most human cancers might be due to a synergistic action of upregulated Skp2 mRNA levels with a concomitant evasion of Cdh1-mediated degradation." (PMID 19549334, 2009). "Moreover, recent studies have showed that Skp2 also regulates other cell cycle regulators that may contribute to cancer progression, including c-Myc, cyclin E, p57Kip2, p21WAP1, and E2F1." (PMID 18644126, 2008). "Several studies have provided evidence that both the Skp2 and Cks1 may have important roles in the development of tumor aggressiveness and its expression may be used as an independent prognostic factor for survival in various carcinomas." (PMID 18922157, 2008). "However, the role of APC/C activity in the regulation of Skp2 levels in human cancers is at present unknown." (PMID 16859513, 2006). "Thus, the identification of novel therapeutic interventions that may down-regulate the expression of Skp2 in cancer may potentially lead to a significant decrease in cancer progression and control of the disease." (PMID 16859513, 2006). "Another inhibitor of SKP2, SZL-P1-41, is also found to inhibit the cancer progression and reduce the cancer stem cell population." (PMID 41385185, 2025). "On one hand, SKP2 was transcriptionally activated by C‐MYC, thereby decreasing p27 to promote G1/S transition and cancer cell growth." (PMID 40051297, 2025). "SKP2, another substrate adaptor of the CUL-RING ligase family, targets tumor suppressors p21 and p27 for proteasomal degradation in cancer." (PMID 39851497, 2025). "In the cancer pathway, five genes (WNT1, DLL, TRAF1, GST, and GADD45) were upregulated, while CASP3, IKBKA, STAT5A, RPS6KA5, BIRC5, BIRC2/3, and SKP2 were downregulated." (PMID 40723320, 2025). "FBXW2 has been reported to reduce expression of several proteins associated with malignant tumor states, such as β-catenin, SKP2, NF-κB p65 and EGFR, which contribute to cancer stemness, tumorigenesis and metastasis." (PMID 40721413, 2025). "This gene usually inhibits the growth of cancer cells by suppressing oncogenes (HER2, c-Myc, Skp2) and increasing the P21 tumor suppressor gene." (PMID 39315286, 2024). "Notably, the possible mechanisms of SKP2 expression in cancers may be complex." (PMID 37308972, 2023). "Consistent with the known features of Skp2 and HIF-1α as metastasis enhancers in various types of cancers, Mint3 promotes epithelial–mesenchymal transition in a HIF-1α- and Skp2-dependent manner with an enhancing effect on the expression of the Slug protein." (PMID 36831085, 2023). "Analyzing a panel of cancer cell lines, RMS cells have the highest levels of SKP2, mirroring the results in RMS patients." (PMID 38102140, 2023). "Skp2, a part of the E3 ubiquitin ligase SCF, especially encourages the ubiquitination degradation of the p27 and supports the development of cancer cells in various cancers." (PMID 37240281, 2023). "PAQR4 inhibits SKP2-mediated ubiquitination of CDK4 by competitive binding to the binding site, contributing to cancer cell proliferation and carcinogenesis." (PMID 36609413, 2023). "To date, growing evidence indicates that overexpression of Aurora A/B, cyclin D/E, Cdc20, Skp2, and PLK1 has been frequently detected in all kinds of cancers, and these oncoproteins serve as effective therapeutic targets in the clinic." (PMID 37274251, 2023).
cancer (continued). "Skp2 inhibitor SZL P1–41 restricts cancer stem cell traits and cancer progression by selectively suppressing Skp2 ubiquitin ligase activity." (PMID 35301297, 2022). "Consistent with this notion, several small molecules targeting the Skp2 SCF complex were recently identified and proven to be promising for treating human cancers." (PMID 36180910, 2022). "Taken together, SKP2, as the target of YAP, promotes cell proliferation in the cell cycle process of pan-cancer." (PMID 35685435, 2022). "As Ki67 was a vital important proliferation indicator in the cell cycle, we assessed the relationship between SKP2 and MKI67 mRNA in pan-cancer using TIMER database." (PMID 35685435, 2022). "Thus, reduced SKP2 expression may adversely impact SCF complex function and underlie the accumulation of protein substrates whose increased abundance promotes CIN and contributes to cancer pathogenesis." (PMID 36496990, 2022). "The remaining four types of cancer, including LAML, MESO, THYM, and UVM, lack the expression data of SKP2 in normal tissue." (PMID 35685435, 2022). "Interestingly, Skp2 overexpression is correlated with Akt hyperactivation, suggesting that Skp2 and Akt may act in a linear pathway or act in concert to facilitate cancer development." (PMID 36180910, 2022). "Of note, we confirmed that SKP2 was a target of YAP and involved in the proliferation of tumor cells in the cell cycle process of pan-cancer by bioinformatic analysis." (PMID 35685435, 2022). "Collectively, these results indicated that the overexpression of Skp2, as the target of YAP, promotes the growth of cancer cells." (PMID 35685435, 2022). "In our study, SKP2 was validated as the downstream target of YAP involved in cell cycle progression in cancer, which was consistent with previous research that YAP directly regulates SKP2 transcription." (PMID 35685435, 2022). "Although not all F-box proteins have good characteristics, many F-box proteins, such as SKP2, FBXW7, FBXO4, and FBXO32, are related to the cancer development and progression and cancer cachexia." (PMID 34950036, 2021). "Next, CNA analyses revealed that each gene is frequently altered in 10 common cancer types, and that SKP1, RBX1, FBXW7 and FBXO5 tend to exhibit more losses, while CUL1 and SKP2 exhibit more gains." (PMID 35008511, 2021). "The substrates of Skp2 often are tumor suppressors including p21, E-cadherin, p27, p57, FOXO1 and p130 in human cancer cells." (PMID 33621206, 2021). "Secondly, as a tumor suppressor, FOXP3 represses many key target genes in cancer development and progression, such as HER2/ERBB2, BRCA1, SKP2, and CD44, providing a strong link between FOXP3 and cell cycle regulation as well as FOXP3 and DNA repair system." (PMID 34768829, 2021). "We found that SIRT7 compromises SKP2-mediated AKT activation in the cytoplasm, thus inhibiting malignant tumor progression." (PMID 34433808, 2021). "Data of the GEO database revealed that HRAS oncogenic signature were enriched in Gins1 high-expressed cancer cells, and silencing GINS1 decreased RAS, SKP2 and LIF expression in our experiments." (PMID 34414190, 2021). "Therefore, Skp2 inhibitors may exert a certain effect on cancer immunotherapy regulation." (PMID 34943817, 2021). "Drugs targeting components of various cancer-related SCFs, including FBXW7, SKP2, FBXO3, FBXL3, and β-TrCP1, have been developed." (PMID 34203106, 2021). "Among 12 genes reported in the literature as SL with RB1 6 genes (PPWD1, SKP2, AURKA, AURKB, E2F1, and E2F3) scored as SL RB1 partners in human cancer patients." (PMID 33591981, 2021). "Other E3 ubiquitin ligases including Skp2 and KLHL22 are oncoproteins, which are overexpressed in many cancers." (PMID 33670113, 2021).